IL7 (interleukin 7)
Diseases named in the same sentence as IL7 in open-access papers (continued):
Sharing a sentence is not in itself a finding about the gene and the disease.
dengue (10 papers, 2008 to 2025). "By both univariate and multivariate analysis, we show that the most prominent features of severe dengue are lower type I and type II interferons, IL-7, sCD40L and increased production of IL-6, IL-8, IL-10 and VEGF." (PMID 26982706, 2016). "Together with other chemotactic effectors (CXCL9/10/11) and immune cell response-modulating cytokines (IL-6, IL-7 and BAFF), RANTES has been associated with immune enhancement and increased vascular permeability following dengue virus infection." (PMID 28006034, 2016). "Our data also suggests a possible link between dengue virus infection leading to suppression of pro-survival cytokine IL-7 and T-cell homeostasis." (PMID 26982706, 2016). "IL-1β, IFN-γ, IL-4, IL-6, IL-13, IL-7 and GM-CSF were significantly increased in patients with severe clinical manifestations (severe dengue) when compared to mild disease forms (mild dengue)." (PMID 18578883, 2008). "IL-7, important for B and T cell development, was found to be highly expressed in patients with warning signs throughout the disease and this was also observed in a severe dengue cohort from Brazil." (PMID 24647042, 2014). "Other cytokines/chemokines that showed a borderline significant increase in acute dengue compared with healthy ones were IP-10, MIP-1β, and IL-7." (PMID 34734091, 2021). "We observed that cytokine concentrations of IL-1β, IFN-γ, IL-4, IL-6, IL-7, IL-13 and GM-CSF were significantly increased during severe dengue as compared to mild dengue, while MIP-1β levels are higher in mild dengue." (PMID 18578883, 2008). "Many studies have investigated the cytokines patterns in serum samples in patients with DHF and these studies have shown that TNFα, IL-6, IL-10, IL-1β, IFN-γ, IL-4, IL-13, IL-7, GM-CSF, MIF, along with several other cytokines were elevated in patients with DHF when compared to dengue fever (DF)." (PMID 23209731, 2012). "Plasma concentrations of n = 43/48 markers were found to be significantly different between dengue patients and healthy controls, except for n = 5/48 markers including TRAIL (p = 0.082), TNF‐beta (p = 0.991), GM‐CSF (p = 0.405), IL‐5 (p = 0.078), and IL‐7 (p = 0.051)." (PMID 40704559, 2025).
pulmonary fibrosis (10 papers, 2009 to 2024). Chronic progressive interstitial lung disorder characterized by the replacement of the lung tissue by connective tissue, leading to progressive dyspnea, respiratory failure, or right heart failure. "Collectively, these data demonstrated that pulmonary local IL-7 intervention restrained CS-induced pulmonary fibrosis by disrupting the TRM-Teff maintenance and function, highlighting the important role of TRM-Teff in mediating silicosis." (PMID 39122899, 2024). "There was found a significant increase in the BAL fluid levels of IL-4, IL-6, IL-7, and IL-8, and a significant relationship with pulmonary fibrosis in the patients, hence the role of BAL fluid cytokines in ILD pathophysiology." (PMID 37670355, 2023). "Our results are consistent with in vitro and in vivo molecular evidence demonstrating that IL-7 inhibits fibroblast TGF-ß production in pulmonary fibrosis." (PMID 35715807, 2022). "The antifibrotic effect of IL-7 is reflected by an improvement of bleomycin-induced pulmonary fibrosis through IL-7." (PMID 19615053, 2009). "We demonstrated that IL-7 neutralization in the lung was effective in alleviating CS-induced pulmonary fibrosis by decreasing pathogenic CD4+ TRM-Teff cells but not TRM-Tregs expressing low IL-7R." (PMID 39122899, 2024). "Reversely, the successful postponed pulmonary fibrosis under anti-IL-7 blocking might also contain the decreased maintenance of Th9 cells." (PMID 39122899, 2024). "EMT, TGF-β, hyperproliferation of myofibroblasts and high levels of pro-inflammatory IL-2, IL-7, and IFN-γ, are extensively involved in pulmonary fibrosis during SARS-CoV-2 infection." (PMID 39469708, 2024). "In his view, the IL-7 antagonism of TGF-β and the resulting block of fibrosis observed in an experimental model (bleomycin-induced lung fibrosis) could represent an interesting aspect of IL-7 activity which remains to be demonstrated in the clinic." (PMID 22383042, 2012).
T-cell acute lymphoblastic leukemia (10 papers, 2018 to 2025). Acute lymphoblastic leukemia of T-cell origin. "It was previously reported that ROS induced by mitochondrial respiration and NADPH oxidase contributes to the survival of T-cell acute lymphoblastic leukemia cells by being associated with IL-7-mediated signaling." (PMID 33800509, 2021). "In T-cell ALL, interleukin-7 activates the phosphoinositide 3-kinase/Akt/mammalian target of rapamycin pathway and mediates ROS-dependent T cell proliferation and growth." (PMID 36747147, 2023). "In human T-cell acute lymphoblastic leukemia cells, IL-7-induced generation of ROS is reportedly involved in PI3K-AKT signaling, which aids survival." (PMID 33800509, 2021). "Furthermore, the IL-7–IL-7R axis is involved in hematological cancers, including T-cell acute lymphoblastic leukemia, chronic lymphocytic leukemia, and Hodgkin’s lymphoma." (PMID 35159120, 2022). "Previously, IL-7 has been reported to activate other pathways that could affect embryo development, such as JAK/STAT and MAPK signaling pathways in lymphocytes and T-cell acute lymphoblastic leukemia cells." (PMID 40263539, 2025). "Reportedly, IL-7 activates the JAK/STAT, PI3K/Akt, and mitogen-activated protein kinase/extracellular signal-regulated kinase (MAPK/ERK; MEK) pathways in normal T cells and T-cell acute lymphoblastic leukemia cells." (PMID 36570506, 2022).
AIDS (9 papers, 2010 to 2024). A syndrome resulting from the acquired deficiency of cellular immunity caused by the human immunodeficiency virus (HIV). "High IL-7 plasma levels as well as decreased membrane-associated (m)IL-7R expression of T cells were found in AIDS patients with immune failure." (PMID 28582466, 2017). "Impaired IL-7 signalling has been associated with diminished IL-7Rlow expression of T cells from AIDS patients, but different mechanisms about the role of STAT5 were described." (PMID 28582466, 2017). "T-cell exhaustion was found in AIDS patients and was associated with decreased IL-7R expression and impaired IL-7 response." (PMID 28582466, 2017). "Among acquired immune deficiency syndrome (AIDS) patients, the reduced count of T cells in SLOs will lead to the reduced secretion of LT-B and thus impact the secretion of IL7." (PMID 26161081, 2015). "Owing to these unique biological properties, IL-7 is currently under clinical investigation as an immune-reconstitution agent in various forms of natural and iatrogenic immunodeficiencies, including those associated with AIDS and cancer." (PMID 22511868, 2012). "Chronic inflammation and increased IL-6 serum concentrations were found in AIDS patients with impaired T-cell immunity to IL-7." (PMID 28582466, 2017). "Several mechanisms and T-cell phenotypes were described to play a role in impaired IL-7 functions of AIDS patients." (PMID 28582466, 2017). "Strong evidence for impaired IL-7 regulation and T-cell function was found for chronic viral infections, especially AIDS." (PMID 28582466, 2017). "Chronic inflammation and increased serum concentrations of IL-6 were found in HIV/AIDS, and functional in vitro assays indicated inhibitory effects of the pro-inflammatory cytokines IL-6 and IL-1β on IL-7-mediated signal transduction." (PMID 28582466, 2017). "In AIDS patients—especially those who fail to reconstitute T-cell numbers during therapy—impaired IL-7-promoted T-cell functions indicated T-cell exhaustion/senescence." (PMID 28582466, 2017). "Recently, persistent inflammation characterised e.g. by increased IL-6 serum concentrations from AIDS patients were found to correlate with T-cell exhaustion/senescence and impaired T-cell response to IL-7." (PMID 28582466, 2017). "In AIDS patients increased IL-7 plasma levels and decreased mIL-7R expression of T cells were described." (PMID 28582466, 2017). "During the follow-up period, 4 animals (two untreated and two IL-7-treated) developed early signs of progression to AIDS (rapid progressors [RP]) and were euthanized for terminal disease within 5 months of infection." (PMID 22511868, 2012). "Further studies on the regulatory pathways behind bone marrow IL-7/IL-7R production and IL-7Rα-mediated signaling in HIV/AIDS patients are needed to identify the most efficacious clinical use of IL-7 in the (adjuvant) treatment of HIV-positive patients." (PMID 21209878, 2010). "For raising CD4+ and CD8+, recombinant IL-7 and immune checkpoint inhibitors for relapsing VL might be conducted for patients with relapsing VL and AIDS." (PMID 38921748, 2024). "Our data suggest a scenario where proliferative responses to IL-7 would be favored in a narrow window of time upon thymic egress, which has important implications to the therapeutic use of IL-7 in clinical settings known to be associated with thymic injury, namely, HIV/AIDS and chemotherapy." (PMID 28154568, 2017). "Furthermore, impaired T-cell response to IL-7 in AIDS patients was shown to affect immune reconstitution during anti-retroviral therapy." (PMID 28582466, 2017). "High IL-7 plasma levels and low mIL-7R expression of T cells have previously been described for HIV/AIDS patients." (PMID 28582466, 2017).
bacterial sepsis (9 papers, 2018 to 2024). "This is in line with current clinical trials, in which immune stimulatory therapies (e.g., with IL-7, GM-CSF, check-point inhibitors) were beneficial for patients with bacterial sepsis." (PMID 36851312, 2023). "Similar alterations have been described in bacterial sepsis and therapeutic strategies targeting T cell function such as recombinant human interleukin 7 (rhIL-7) have been proposed in this clinical context." (PMID 35246776, 2022).
experimental autoimmune encephalomyelitis (9 papers, 2013 to 2025). An autoimmune demyelinating disease of the central nervous system that is produced experimentally in animals by the injection of homogenized brain or spinal cord in Freund's adjuvant. "Very recently, it was reported that IL-7 could promote the development of a unique subset of GM-CSF and IL-3-producing T cells (“Th-GM”) in mice and this was associated with encephalitogenicity in the experimental autoimmune encephalomyelitis model." (PMID 29075267, 2017). "In experimental autoimmune encephalomyelitis (EAE), a murine model of MS, administration of sCD127 with IL‐7 increased the bioactivity of IL‐7 and was associated with increased disease severity." (PMID 34525268, 2021). "Ligation of IL7R by IL-7 was found to be required for autoimmune neuroinflammation in experimental autoimmune encephalomyelitis." (PMID 31023360, 2019). "Moreover, blocking IL-7 signaling in myelin-specific CD4 T cells by αIL-7Rα significantly delays experimental autoimmune encephalomyelitis (EAE) onset and reduces disease severity." (PMID 27912762, 2016).
metabolic syndrome (9 papers, 2016 to 2025). A cluster of metabolic risk factors for CARDIOVASCULAR DISEASES and TYPE 2 DIABETES MELLITUS. "Of note, metabolic syndrome was also associated with lower levels of IL-2 (−2.81 pg/mL), IL-7 (−17.7 pg/mL) and IL-10 (−2.18 pg/mL)." (PMID 39404367, 2024). "Comorbidities as sleep disorders, metabolic syndrome, number of cigarettes smoked, and daily alcohol consumption have been associated with decreased levels of IL-7." (PMID 31827384, 2019). "Both population studies found that exposure to SO42− affected levels of IL-1β, IL-5, IL-7, IL-12, and IFN-γ, increasing the risk of metabolic syndrome, suggesting that SO42− affects systemic inflammation and metabolic disease." (PMID 39195631, 2024). "Similarly, JUNB’s connection to the IL-6 and IL-7 pathways highlights the direct link between overexpression of IL-6 and metabolic syndrome development, suggesting JUNB’s role in metabolic status regulation through IL-6 signaling modulation." (PMID 40918148, 2025). "In particular, treatment with risperidone, as the least atypical antipsychotic, led to an increase in pro-inflammatory IFN-α2, IL-1β, and IL-7 in schizophrenia patients with metabolic syndrome and was ineffective in lowering pro-inflammatory cytokines in patients without it." (PMID 37239308, 2023).
Stroke (9 papers, 2019 to 2025). Sudden impairment of blood flow to a part of the brain due to occlusion or rupture of an artery to the brain. "Previous study suggested that the levels of IL-7 were decreased in severe stroke patients, and the decrease in IL-7 levels is associated with poor prognosis in patients." (PMID 39763672, 2024). "We found that the level of serum IL-7 was notably reduced in patients with severe stroke and poor outcome." (PMID 31164999, 2019). "Controversially, other studies showed that IL-7 level was significantly reduced in stroke patients compared to controls." (PMID 31164999, 2019). "In our study, the salivary concentration of IL-2, IL-5, IL-7, IL-10, IL-12 (p70), IL-13, IL-15, and IFN-α2 was below the detection level in healthy controls (most commonly) and in stroke patients." (PMID 40520895, 2025). "After a stroke, adhesion molecules (e.g., ICAM-1) mediated several leukocytes and cytokines (e.g., VEGF and IL-7) entered into the brain through the injured blood-brain barrier." (PMID 35720096, 2022). "Of note, the AUCs for GDF-15, D-dimer, ADAMTS13, CCL2/MCP-1, IL-4, CC4b, IL-7, ferritin, SAA, CCL1/I-309 and IL-10 were ≥0.75 in indicating stroke amongst children with TBM." (PMID 33930055, 2021). "Notch pathway was involved in AST induced differentiation of NSCs, NGF, IL-7, and BDNF-TrkB pathway took part in proliferation and the neuronal differentiation of NSCs after stroke in vivo." (PMID 33716673, 2021). "Overall, main FD features including hypertrophic cardiomyopathy, venous thrombosis, arterial thrombosis, and stroke, cornea verticilata, and renal (chronic kidney disease stage) events are partly explained by FGF2, IL-7, VEGFA, and VEGFC plasma levels." (PMID 32370284, 2020). "The intersection of the top 10 genes from the two stroke outcomes are seven genes with T2DM, these include CCR4, IFNA2, IL-9, IL-7, IL-5, CCR3, and IL-27." (PMID 32010048, 2019). "The seven important predictor genes (CCR4, IFNA2, IL-9, IL-7, IL-5, CCR3, and IL-27) that overlapped both stroke outcomes had mean fold change ranging from 3.98 to 35.06." (PMID 32010048, 2019). "We initially screened 35 inflammatory mediators in 75 patients, and found that IL-4, IL-7, IL-9, GM-CSF and MIP-1α were significantly decreased in the severe stroke group, compared with control group (P < 0.05; data not shown)." (PMID 31164999, 2019). "In addition, we observed trends (0.05<p-value≤0.09) in increased levels of GDNF, interleukin (IL)-7, MMP-9, lipocalin-2, IL-4, sP-selectin, and myoglobin, and lower levels of CC5a, in children with TBM-related stroke compared to TBM without stroke." (PMID 33930055, 2021).
bladder cancer (8 papers, 2010 to 2026). "Other pathways found in three of the datasets include the pyrimidine metabolism, tAminoacyl-tRNA biosynthesis, DNA replication, IL-7 Signaling and bladder cancer pathways." (PMID 20964848, 2010). "Next, we examined the mutations in these genes in bladder cancer and found that the mutation frequency of PTGER4 was the highest, reaching 9%, with amplification mutations as the main mutation; it was followed by RUNX1, IL7, and CIITA, with mutation frequencies of 6, 5, and 5%, respectively." (PMID 32655621, 2020). "An initial screen included a bladder cancer panel with 16 proteins (MCP‐1, MIP‐1α, MIP‐1β, IP‐10, IFN‐α, IL‐1α, IL‐1RA, IL‐8, IL‐7, IL‐31, IL‐15, TNF‐β, Eotaxin, SDF‐1α, Rantes, and GRO)." (PMID 38553868, 2024). "Moreover, IL-7 promotes cell migration and invasion by upregulating Erk1/2-mediated MMP-9 expression in bladder cancer cells." (PMID 36672342, 2023). "There are few reports on the role of IL-7 and HDAC7 in bladder cancer." (PMID 32655621, 2020).
Crohn disease (8 papers, 2012 to 2026). A gastrointestinal disorder characterized by chronic inflammation involving all layers of the intestinal wall, noncaseating granulomas affecting the intestinal wall and regional lymph nodes, and transmural fibrosis. "Among the 81 queried DEGs related to Crohn’s disease, 7 genes (IL-7, GATA3, CD28, CD5, TXN, ETS-1, and CCR7) were introduced as dysregulated genes." (PMID 33585004, 2020). "In adenomas, IL-7 elevation was associated exclusively with villous growth pattern, while in IBD, circulating IL-7 reflected clinical activity of Crohn’s disease and ulcerative colitis." (PMID 27866242, 2017). "Still, IL-7 weakly corresponded with clinical activity of both Crohn’s disease and ulcerative colitis." (PMID 27866242, 2017). "Secondly, elevated serum concentrations of IL-7 have been detected in patients with ulcerative colitis and Crohn’s disease, and gastric tissue biopsies from patients infected with H. pylori have increased IL-7 message." (PMID 23057802, 2012). "Through network analysis, we can introduce IL-7, GATA3, TXN, ETS-1, CCR7, CD28, and CD5 as Crohn’s disease-related critical genes and possible biomarker panel." (PMID 33585004, 2020).
Hypertension (8 papers, 2020 to 2025). The presence of chronic increased pressure in the systemic arterial system. "This study focuses on the role of hypertension and dysfunctional interleukin 7 in PTSD and CVD, the former caused by stress-induced sympathetic arousal and elevated angiotensin II, while the latter links stress to premature endothelial cell senescence and early vascular aging." (PMID 37218755, 2023). "Although a study did find IL-7 to be higher in participants with hypertension than in the control group, research into the relationship of these mediators with BP remains limited." (PMID 33392493, 2020). "Additionally, this study described some common underlying mechanisms of hypertension and anxiety, including IL-6, IL-7, ROS, and gut dysbiosis, which are expected to become therapeutic targets for patients with comorbid hypertension and anxiety." (PMID 37273529, 2023). "Moderate positive correlations of the T2 with IL-7 (ρ = 0.455; p = 0.033), IL-10 (ρ = 0.578; p = 0.005), IL-12P40 (ρ = 0.500; p = 0.018), and IL-17A (ρ = 0.452; p = 0.035) levels were observed only in patients without hypertension." (PMID 39685774, 2024). "The comparison of OSA patients without any other diseases with OSA patients with only hypertension also demonstrated increased concentrations of CCL3 and, additionally, increased concentrations of CX3CL1/Fractalkine and IL-7." (PMID 36769452, 2023). "In addition, the comparison of OSA patients without any other disease with OSA patients with only hypertension also demonstrated increased levels of CXCL2/GRO-ß and IL-7." (PMID 36769452, 2023).